PCSK9 (proprotein convertase subtilisin/kexin type 9)
Diseases named in the same sentence as PCSK9 in open-access papers (continued):
Sharing a sentence is not in itself a finding about the gene and the disease.
Sepsis (continued). "PCSK9 antibody therapy was effective in SARS-CoV-2 infection but did not protect against infection and inflammation in sepsis." (PMID 40265438, 2025). "In addition, PCSK9 inhibitors may not benefit young hosts with sepsis." (PMID 36230934, 2022). "While decreased Proprotein Convertase Subtilisin/Kexin type 9 (PCSK9) function improves clinical outcomes in murine and human sepsis, the mechanisms involved have not been fully elucidated." (PMID 27171436, 2016). "Thus, if PCSK9 inhibition had a similar beneficial effect on clinical outcomes as PCSK9 LOF genotype, it may not be necessary to identify the causative organism as Gram positive or Gram negative when considering PCSK9 inhibition as a novel early intervention for sepsis." (PMID 31332258, 2019). "However, PCSK9 in plasma did not correlate with age, and the correlation coefficient r was—0.194 (p = 0.271) for the controls and was 0.022 (p = 0.781) for the SIRS/sepsis group, respectively." (PMID 37515197, 2023).
type 2 diabetes (76 papers, 2013 to 2026). "Assessing possible long-term effects is particularly relevant, as there are concerns about PCSK9 inhibitors exhibiting adverse neurocognitive effects as well as increasing the risk of type 2 diabetes and cancer." (PMID 37903942, 2024). "For example, studies on the proprotein convertase subtilisin/kexin type 9 (PCSK9) inhibitors identified an increased risk of type 2 diabetes, diastolic blood pressure, type 1 diabetes, peptic ulcer disease, and depression." (PMID 38580710, 2024). "One example is the use of PCSK9 SNPs to mimic the low-density lipoprotein cholesterol-lowering PCSK9 inhibitor drug, where genetic evidence showed an additional association with increased risk of type-2 diabetes." (PMID 36829050, 2023). "Mendelian randomization had previously proved that the reduction of LDL-C due to genetic variation at PCSK9 does increase the risk of type 2 diabetes." (PMID 37900173, 2023). "At present, the exact mechanism by which PCSK9 inhibitors increase the risk of type 2 diabetes is unclear." (PMID 37900173, 2023). "The present study indicated that CT + TT genotype and CT genotype of rs2483205, as well as GA + GG genotype of rs2495477 in PCSK9 gene were associated with an increased risk of type 2 diabetes in the Uygur population in Xinjiang." (PMID 35733117, 2022). "PCSK9 blockage has also been linked to visceral adiposity, insulin resistance and a higher risk for type 2 diabetes, all of which contribute to NAFLD." (PMID 35162992, 2022). "In the present study, our primary objective was to assess the association between the single-nucleotide polymorphisms in the PCSK9 gene and type 2 diabetes in Uygur subjects, in Xinjiang, China." (PMID 35733117, 2022). "Incidence of type 2 diabetes was also higher in carriers of the loss-of-function PCSK9 R46L variant, which is associated with low LDL-cholesterol levels." (PMID 35162992, 2022). "The data extracted from our cohort study do not support the findings that the gain-of-function mutations of PCSK9 predispose to the incidence of type 2 diabetes." (PMID 34380558, 2021). "In this study, PTX3, an essential component of innate immunity, and a novel cardiovascular risk factor, also in patients with type 2 diabetes was the strongest predictor of PCSK9 levels in multiple stepwise regression analysis." (PMID 35024053, 2021). "In line with this evidence, Mendelian randomization studies also confirmed the association of PCSK9 variation with the increased risk of type 2 diabetes." (PMID 34380558, 2021). "This study aimed to investigate the relationship between the PCSK9 rs615563 variant with the incidence of type 2 diabetes." (PMID 34380558, 2021). "Although some studies suggest a possible association between PCSK9 genetic variants and an increased risk of type 2 diabetes, there are also studies with contradictory findings." (PMID 34380558, 2021). "In stratified analyses, the positive associations between PCSK9 and the risk of incident type 2 diabetes remained consistent across all subgroups." (PMID 33302966, 2020). "Among 479,522 individuals of UK Biobank, those carrying the LDL-lowering T allele variant rs1159147 of the PCSK9 gene, had a concomitant higher risk of type 2 diabetes and depression." (PMID 33143700, 2020). "We used Cox proportional hazards models with the lowest PCSK9 quartile group (PCSK9 < 220.20 ng/mL) as a reference to further assess the relationship between PCSK9 level and the risk of incident type 2 diabetes." (PMID 33302966, 2020). "In this population-based cohort study, we found a significantly positive association between circulating PCSK9 level and the risk of incident type 2 diabetes in female subjects with prediabetes." (PMID 33302966, 2020). "The association of circulating PCSK9 levels with the risk of incident type 2 diabetes was assessed by Cox regression analysis." (PMID 33302966, 2020).
type 2 diabetes (continued). "In summary, our population-based longitudinal study identified a positive association between circulating PCSK9 levels and the risk of incident type 2 diabetes in female subjects with prediabetes." (PMID 33302966, 2020). "For example, data from a genetic study showed that PCSK9 variants were associated with an increased risk of type 2 diabetes." (PMID 33302966, 2020). "Multivariate Cox regression models with restricted cubic spline analyses revealed that the risk of incident type 2 diabetes increased with increasing PCSK9 level on a continuous scale in female subjects after adjusting for potential confounders." (PMID 33302966, 2020). "Elevated circulating PCSK9 levels are associated with an increased incidence of type 2 diabetes in female subjects with prediabetes." (PMID 33302966, 2020). "The aim of this study was to examine the association of circulating PCSK9 levels and risk for the development of type 2 diabetes in individuals with prediabetes." (PMID 33302966, 2020). "The aim of the study was to investigate associations between physical activity and plasma PCSK9 in subjects with high risk for type 2 diabetes (T2D)." (PMID 31114503, 2019). "In conclusion, genetic variants in PCSK9 that associate with lower concentrations of LDL cholesterol are also associated with a modestly higher risk of type 2 diabetes and with associated differences in measures of glycaemia and bodyweight." (PMID 27908689, 2017). "In a recent study, investigators used a single SNP in PCSK9 and also reported evidence of an association with type 2 diabetes (OR 1·19, 95% CI 1·02 to 1·38; per 1 mmol/L reduction in LDL cholesterol)." (PMID 27908689, 2017). "Given these overlapping results, further trial data are required to assess the risk of type 2 diabetes associated with the use of PCSK9 inhibitors." (PMID 29040597, 2017). "Exploring the PCSK9 associations with incident or prevalent type 2 diabetes separately showed directional concordance of this effect (incident type 2 diabetes OR 1·15, 0·76 to 1·72; prevalent type 2 diabetes OR 1·26, 0·88 to 1·80)." (PMID 27908689, 2017). "The link to type 2 diabetes is further supported by studies of the PCSK9 rs11591147 LoF variant." (PMID 37903942, 2024). "However, some lipid-lowering drugs, such as PCSK9 inhibitors, have various effects, including reducing the risk of cancer and increasing the risk of type 2 diabetes." (PMID 39050670, 2024). "This association remained after extensively adjustment for potential confounders and stratification of several potential risk factors that may have an effect on the PCSK9-type 2 diabetes relationship." (PMID 33302966, 2020). "Above the inflection point at 375 ng/mL, the risk of incident type 2 diabetes increased with increasing PCSK9 levels in female subjects (1.90 [1.06-3.40] at 400 ng/mL, 2.14 [1.21-3.78] at 450 ng/mL, 2.31 [1.31-4.10] at 500 ng/mL, and 2.50 [1.29-4.86] at 550 ng/mL)." (PMID 33302966, 2020). "First, the use of a single baseline PCSK9 measurement to predict outcomes was a simplified and practical approach, though it did not allow us to assess the relationship between changes in PCSK9 levels and the risk of incident type 2 diabetes." (PMID 33302966, 2020). "Therefore, the current study aimed to investigate the relationship between circulating PCSK9 levels and the risk of incident type 2 diabetes in a large-scale prospective cohort of Chinese adults with prediabetes." (PMID 33302966, 2020). "Before this and other PCSK9 inhibitor trials, there had been concerns that PCSK9 inhibitors may have similar effects in terms of type 2 diabetes risk as statins." (PMID 29040597, 2017). "We found that there was evidence for causal associations between PCSK9 inhibitor instrument and lifetime smoking index [β = 0.02 [95% CI, 0.00, 0.03]; P = 0.028]; waist-to-hip ratio (β = 0.05 [95% CI, 0.03, 0.07]; P = 7.26 × 10−6]; type 2 diabetes risk [OR = 1.28 [95% CI, 1.09–1.51]; P = 0.002]." (PMID 34712689, 2021).
type 2 diabetes (continued). "Notably, several studies showed that LDL-cholesterol-lowering PCSK9 (rs11583680, rs11591147, rs2479409, and rs11206510) genetic variants were associated with higher circulating fasting glucose levels and increased risk of type 2 diabetes." (PMID 34041285, 2021). "Thus, further studies are necessary to clarify the mechanisms underlying the association of PCSK9 with type 2 diabetes and to determine whether high PCSK9 levels are a cause or a consequence of type 2 diabetes or both." (PMID 33302966, 2020). "We identified nine protein–disease associations after MR, sensitivity analyses and colocalization; these included associations of COL6A3 and PCSK9 with CAD, F11 with ischemic and cardioembolic stroke, and SPATA20 with type 2 diabetes." (PMID 39856218, 2025). "Higher circulating PCSK9 levels were found in obese compared with nonobese adult subjects, and female obese subjects with type 2 diabetes had the highest levels of PCSK9 within a group of young adults aged 15 to 26 years." (PMID 38440108, 2024). "Specifically, this finding was consistent across the subgroups of patients with type II diabetes mellitus and hypertension, indicating that PCSK9 inhibitors serve as a protective factor against CA-AKI." (PMID 39055658, 2024). "Evidence from cell and animal studies has also shown that downregulating PCSK9 ameliorates lipid and glucose metabolism in type 2 diabetes." (PMID 33302966, 2020). "The results provide a reasonably accurate and unbiased estimate of the relationship between PCSK9 levels and incident type 2 diabetes." (PMID 33302966, 2020). "The PCSK9-type 2 diabetes relationship was slightly stronger in individuals with higher waist circumference, higher levels of LDL-C, and insulin resistance than in their counterparts." (PMID 33302966, 2020). "In the highest PCSK9 quartile, the HR was 2.31 (95% CI 1.24–4.31; p < 0.001 for the trend) for incident type 2 diabetes after adjusting for age, lifestyle factors, physical activity, and educational attainment (model 2)." (PMID 33302966, 2020). "Along this line, further long-term studies are needed to determine the relationship between PCSK9 and the incidence of type 2 diabetes among male individuals." (PMID 33302966, 2020). "Using the PCSK9 GS, 1 mmol/L lower LDL cholesterol was associated with an increased risk of type 2 diabetes (OR 1·29, 95% CI 1·11 to 1·50)." (PMID 27908689, 2017). "Clinical studies show that use of the two PCSK9 antibodies alirocumab and evolocumab potently lowers Lp(a), the latter also in patients with type 2 diabetes." (PMID 28176216, 2017). "Investigators of ongoing and future randomised controlled trials of PCSK9 inhibitors should carefully monitor changes in metabolic markers, including bodyweight and glycaemia, and the incidence of type 2 diabetes in study participants." (PMID 27908689, 2017). "In this mendelian randomisation study, genetic variants in PCSK9, used as a proxy for pharmacological inhibition of PCSK9, were associated with lower LDL cholesterol concentration and increased risk of type 2 diabetes." (PMID 27908689, 2017). "Besides the link to lipid metabolism, we discovered or supported plausible connections of genetic regulation of PCSK9 to other traits such as circadian rhythm and type 2 diabetes." (PMID 38532495, 2024). "Conversely, a 2 × 2 factorial Mendelian randomization study including 425,354 participants from the UK Biobank did not observe an association between lower PCSK9 concentrations and type 2 diabetes." (PMID 36383291, 2022). "The importance of PCSK9 to mediate type 2 diabetes has been recently demonstrated." (PMID 35024053, 2021).
type 2 diabetes (continued). "Our analysis identifies several well-known disease-related genes that are not identified by GWAS, including BRCA1 in Breast Cancer, Amyloid Precursor Protein (APP) in Alzheimer’s Disease, INS in A1C measurement and Type 2 Diabetes, and PCSK9 in LDL cholesterol, amongst others." (PMID 32678846, 2020). "Moreover, little is known about the link between circulating PCSK9 levels and incident type 2 diabetes in prediabetic individuals." (PMID 33302966, 2020). "Previous cross-sectional studies have shown higher PCSK9 levels in type 2 diabetes." (PMID 33302966, 2020). "For instance, we detected BRCA1 in Breast Cancer, Amyloid Precursor Protein (APP) in Alzheimer’s Disease, INS in A1C measurement and Type 2 Diabetes, PCSK9 in LDL cholesterol levels and SNCAIP in Parkinson’s Disease, and the circadian rhythm gene CRY2 in Morning vs. Evening chronotype." (PMID 32678846, 2020). "HRs for incident type 2 diabetes were higher with increasing PCSK9 quartile." (PMID 33302966, 2020). "Interestingly, PCSK9 levels are decreased in patients with type 1 as compared to type 2 diabetes, whereas it has been proven that hyperinsulinemia increases PCSK9 expression in murine models." (PMID 32225075, 2020). "The MR study found PCSK9 variants to have a similar effect as HMGCR variants on the risk of cardiovascular events (OR 0.81, 0.74–0.89 vs OR 0.81, 0.72–0.90) and the risk of type 2 diabetes (OR 1.11, 1.04–1.19 vs 1.13, 1.06–1.20) for each 10 mg per dl decrease in LDL cholesterol level." (PMID 29040597, 2017). "Interestingly, PCSK9 concentration is decreased in patients with type 1 as compared to type 2 diabetes, which goes along with data in obese mice with pharmacologically-induced insulin deficiency showing a reduced PCSK9 expression." (PMID 28176216, 2017). "PCSK9 variants associated with lower LDL cholesterol were also associated with circulating higher fasting glucose concentration, bodyweight, and waist-to-hip ratio, and an increased risk of type 2 diabetes." (PMID 27908689, 2017). "Therefore, we speculated that the role of PCSK9 in the progression of type 2 diabetes and metabolic disorders could be mediated by insulin." (PMID 29343301, 2018). "We found that fat mass independently increased plasma levels of all protein mediators (COL6A3-derived endotrophin, F11, PCSK9, C1R and SPATA20) and increased the odds of type 2 diabetes, CAD and ischemic stroke." (PMID 39856218, 2025). "The effect of PCSK9 inhibition on TRL metabolism has been studied in healthy individuals and in patients with type 2 diabetes." (PMID 33643062, 2021). "Interestingly, recent studies have revealed the pleiotropic effects of PCSK9 inhibitors—a cardiovascular drug that regulates low-density lipoprotein cholesterol—on autoimmune diseases, as well as the impact of APOF on type 2 diabetes." (PMID 40564099, 2025). "Hence, although PCSK9 inactivation can establish low LDL levels, PCSK9 loss-of-function mutations might concomitantly induce adipocyte hypertrophy in visceral fat depots in a subgroup of patients, thereby creating a risk factor for insulin resistance, type 2 diabetes and NAFLD." (PMID 35162992, 2022). "Baseline circulating PCSK9 levels were significantly higher in female subjects developing incident type 2 diabetes than in those not developing incident type 2 diabetes (p < 0.001)." (PMID 33302966, 2020). "Hence, differences in baseline PCSK9 levels in males with and without incident type 2 diabetes may be observed when the follow-up period is longer than 3.1 years." (PMID 33302966, 2020).